IL2 (interleukin 2)
Diseases named in the same sentence as IL2 in open-access papers (continued):
Sharing a sentence is not in itself a finding about the gene and the disease.
Autoimmunity (continued). "AICD, which is essential for the pathogenesis of autoimmunity and autoimmune lymphoproliferative syndrome, occurs mainly because of IL-2 mediated signaling via the death-domain-containing receptor Fas (CD95)." (PMID 16759382, 2006). "Since IL2 (-/-) mice are immunocompromised, it was entirely unexpected to find that a syndrome of lymphocyte hyperactivity and apparent autoimmunity appears as the mice mature beyond puberty." (PMID 15606917, 2004). "Subsequently, we found that IL2 treatment of IL2 (-/-) mice before day 10 after birth prevents the onset of the syndrome of lymphocyte activation and autoimmunity." (PMID 15606917, 2004). "The dose of IL-2 affects the balance between immune tolerance and autoimmunity." (PMID 40181974, 2025). "In addition, low dose IL‐2 supports the survival of regulatory T cells (Tregs) which control inflammation and autoimmunity." (PMID 40172096, 2025). "Low-dose IL-2 therapy, which preferentially expands Tregs, or the use of checkpoint inhibitors targeting co-stimulatory pathways involved in autoimmunity, may provide innovative strategies, though their application in AIG requires rigorous investigation." (PMID 41148791, 2025). "The reduced IL-2 expression in the 3-NP treatment group suggests that 3-NP may impair Treg cell differentiation, probably promoting inflammation and autoimmunity, common in neurodegeneration." (PMID 40038202, 2025). "However, the dysregulation or overactivity of IL-2 can have adverse effects, especially when inflammatory disorders, immunosuppression, and autoimmunity are involved." (PMID 40227240, 2025). "Also, IL2 has been shown to serve an important role in combination therapies for autoimmunity and cancer." (PMID 38741183, 2024). "In this study, we examined how FOXP3+ Treg obtain IL-2 at sites of autoimmune neuroinflammation." (PMID 38378682, 2024). "In systemic lupus erythematosus (SLE), lncRNA H19 is significantly upregulated and inhibits the proliferation of Treg cells and promotes the conversion of Treg cells to Tfh cells through the direct inhibition of IL-2 production, which results in immune dysregulation and exacerbates autoimmunity." (PMID 38715092, 2024). "Tregs are an IL-2-reactive cell type known to control autoimmunity." (PMID 38800484, 2024). "IL-2 is an effector cytokine for T cells and an important NK-cell survival factor but also necessary for Treg survival and the restraint of lethal autoimmunity." (PMID 39403378, 2024). "Results indicated that IL-2/IL-15 and IL-2/IL-21 pretreated groups showed significant autoimmunity against MSCs, which are consistent to the expression of activating receptors and intracellular levels of cytotoxic soluble factors (Supplementary 4) in the NK cell culture." (PMID 38106519, 2023). "In the below chapters, we will discuss recent pre-clinical and clinical efforts to develop IL-2-based immunotherapeutic strategies that target Treg to treat autoimmune conditions characterised by low numbers or reduced suppressive activity of Treg as well as to prevent transplant rejection." (PMID 37741949, 2023). "The activation of effector T cells as the main function of IL-2 was contested when ablation of Il2, Il2ra and Il2rb expression in mice caused lethal lymphoproliferation and autoimmunity, rather than immunodeficiency." (PMID 37741949, 2023). "Neutralisation of IL-2 induces T cell-mediated autoimmunity by selectively reducing Treg numbers." (PMID 37741949, 2023). "IL-2 plays an important role in regulating the imbalance between autoimmunity and immune tolerance." (PMID 37391717, 2023). "In vitro IL‐2 and IL‐15 activities are indissociable when purified CD8+ T cells are used; however, IL‐2 deficiency is associated with lymphoproliferative disorders and autoimmunity." (PMID 36705415, 2023).
Autoimmunity (continued). "In this study, serum IL-2 was elevated in patients with advanced schistosomiasis compared with the healthy controls, which seems to be significant in maintaining the number and function of Treg cells and inhibiting autoimmunity." (PMID 37887717, 2023). "Altogether, these results showed that an IL-2LD–tuned microbiota could be efficiently transplanted to IL-2–naive recipient mice and protected against autoimmunity and gut inflammation in 2 murine genetic backgrounds." (PMID 35917175, 2022). "Therefore, given the success of low-dose IL-2 therapies in autoimmunity, we set out to test low-dose rIL-15 as treatment in a mouse model of NTS, with a specific focus on TEC health and CD8+ T cell involvement." (PMID 36429085, 2022). "T1D associated SNP alleles in UBASH3A increase its expression in primary human CD4+ T cells and inhibit NF-κB signaling, resulting in reduced IL-2 production, which might increase the probability of initiating autoimmunity." (PMID 35812428, 2022). "The Th1 cytokines IL-2 and IL-12 are also important in the defense against infections and cancer, involved in the development of memory responses against pathogens, and in the control of autoimmunity." (PMID 36119067, 2022). "FOXD1 is involved in autoimmunity through its regulation of IFNγ, IL2, IL4, and NFAT complexes." (PMID 35328504, 2022). "Therefore, the dose of IL-2 appears to be a determining factor in the imbalance between immune tolerance and destructive autoimmunity and is important to be established safely before moving forward as a treatment for any disease." (PMID 34685775, 2021). "Although IL-2 is not required for the survival of Tregs, its absence is associated with marked impairment of their function, as well as with the development of autoimmunity." (PMID 34236047, 2021). "In addition, the downregulation of IL2 represents a strong evidence of the inhibition of T cells-mediated autoimmunity because IL2 are produced only by CD4+ and CD8+ T cells." (PMID 34650558, 2021). "Furthermore, IL-2 is essential in immunoregulation, as it regulates autoimmunity via the production of CD4+CD25+ T regulatory (Treg) cells." (PMID 34073791, 2021). "The proinflammatory cytokine, interleukin-2 (IL-2), acts by binding to the IL-2R, influencing T lymphocyte differentiation into effector and memory T cells as well as regulatory T cells which are important for preventing autoimmunity." (PMID 33680514, 2021). "IKZF1 binds the IL-2 gene promoter and represses IL-2 production and proliferation in T cells thus controlling important steps in induction of effective immune responses, regulation of inflammation as well as prevention of autoimmunity." (PMID 33679794, 2021). "Bacterial and viral infections also contribute to autoimmunity in that they could trigger the observed loss of tolerance via TLR signaling, IL-2 reduction or autoreactivity, amongst others." (PMID 35008717, 2021). "In the context of autoimmunity, low-dose IL-2 has been shown to be safe in T1D and SLE." (PMID 32977677, 2020). "However, tacrolimus used to treat autoimmunity blocks IL2 production and is used for active rheumatoid arthritis and lupus nephritis." (PMID 32733557, 2020). "Overall, these data indicate that these FPs have limited utility when administered in IL-2 replete inflammatory environments, which may include environments marked by chronic inflammation and autoimmunity." (PMID 33072087, 2020). "However, the range of conditions that IL‐2 is used to help treat stretches beyond cancer to autoimmunity and chronic infections." (PMID 32480431, 2020). "First, Treg cells were described as a subpopulation of T cells that suppressed the immune response, avoiding autoimmunity, and were characterized by the expression of the alpha chain receptor for IL-2, also called CD25, which had previously been found expressed on activated T cells." (PMID 32674255, 2020).
Autoimmunity (continued). "Indeed, the therapy by low-dose IL-2 or the recombinant form of IL-2 was observed as an effective approach to autoimmune conditions and inflammatory diseases as well as the suppression of tumor growth in pancreatic cancer." (PMID 32075624, 2020). "In this context, it has been shown that defects in IL-2/IL-2R signaling in Treg cells profoundly contribute to the development of autoimmunity since IL-2 has a key role in the control of Foxp3 expression in CD4+CD25+ cells, through the phosphorylation of STAT3 and STAT5 proteins." (PMID 32117202, 2019). "However, Treg-specific deletion of Mcl-1 produced lethal autoimmunity as early as 4 weeks of age, a much shorter time frame than the potential role we detected for Bcl-2 in supporting IL-2-dependent Treg survival." (PMID 30833563, 2019). "As a consequence, the expansion of the CD4+ FOXP3+ Tregs due to elevated IL-2 concentrations likely reflects an attempted compensatory mechanism to regulate Teff cell hyperactivity in an inflammatory environment during these periods of flaring autoimmunity." (PMID 31781109, 2019). "Interestingly, Tregs from CD25−/− Bim−/− mice, where IL-2-dependent survival and function have been uncoupled, were shown to be less suppressive in vitro and unable to prevent autoimmunity in vivo." (PMID 29670626, 2018). "Low doses of the immune signaling molecule interleukin-2 (IL-2) could help suppress unwanted immune responses in patients with autoimmunity." (PMID 29527328, 2018). "Considering the role of IL-2 in the differentiation of TH2 cell subsets, this effect on IL-2 production could represent a genetic risk for asthma and autoimmunity." (PMID 29992143, 2018). "Thus, a threshold of IL-2 signals to Treg cells is needed to program their functional attributes, for their maintenance, and to prevent wasting autoimmunity." (PMID 30560927, 2018). "While reactivation of endogenous retroviral protein expression may elicit serological and cell-mediated responses, an uncontrolled expansion of Treg cells in subjects who lost self-tolerance to IL-2 or IRF5 may explain the development of autoimmunity." (PMID 29379122, 2018). "Therefore, we examined CCR9+/− Th and CCR9+/− Tfh cells in two models of autoimmunity and inflammation, namely the NOD mouse and mice that have been made genetically deficient in IL-2 (Il2−/−mice)." (PMID 30662436, 2018). "The benefit in using systemic low-dose IL-2 has been reported in several autoimmune disorders." (PMID 28708863, 2017). "However, benefit is limited in vivo due to the high affinity of T-regulatory cells for IL-2, which is responsible for NK cell inhibition to prevent autoimmunity, as well as by the short half-life—approximately 10 min—of IL-2 in serum." (PMID 28919894, 2017). "Also, earlier studies have reported severe autoimmunity, colitis and other pathological conditions in Il2−/− mice." (PMID 28415569, 2017). "The absence of IL-2 or IL-2R in mice causes the development of a lethal autoimmunity that lacks a negative regulatory function due to the absence of Treg cells." (PMID 27293315, 2016). "For instance, Th1 cells produce IFN-γ and interleukin-2 (IL-2) and play a role in autoimmunity." (PMID 28116316, 2016). "Therefore, immunesenescence and autoimmunity would prevail in about 30% of infected people due to the low numbers and poor regulatory activity of Tregs that lack IL-2 produced by the pool of effector conventional T cells." (PMID 27242702, 2016). "The concept of LD IL-2 as a therapeutic approach is supported by data in mouse models where autoimmunity is cured and further strengthened by success in human clinical studies in hepatitis C virus-induced vasculitis, chronic graft-versus-host disease, and Alopecia areata." (PMID 26793191, 2015).
Autoimmunity (continued). "These in vitro data are compatible with the in vivo observations that IL-2 administration resulted in autoimmunity or augmented immune responsiveness, but they cannot explain an opposing observation such as IL-2 immunotherapy preventing and reversing IDDM in NOD mouse model." (PMID 26529512, 2015). "Replacement of physiological doses of IL-2 could restore self-tolerance and prevent further autoimmunity by enhancing the function of CD4+ T regulatory cells (Tregs) to limit the activation of auto reactive T effector cells (Teffs)." (PMID 26646829, 2015). "Moreover, vitamin D inhibits expression of Th1 cytokines, such as IL-2, interferon-γ and tumor necrosis factor-α, thus providing protection against autoimmunity." (PMID 25644263, 2015). "A deficiency in IL-2 production or lack of IL-2 responsiveness preferentially leads to a loss of Treg function and an increase in autoimmunity." (PMID 25457307, 2015). "IL-2 is also necessary during T cell differentiation in Treg, which are involved in self antigens recognition, which could result in autoimmunity." (PMID 24734033, 2014). "Targeting Mst1 and Mst1-mediated signaling pathways that control Th1-dependent cytokine release, IL-2 secretion, and lymphocyte proliferation represents a promising alternative to the current approaches to treat autoimmunity, organ rejection and graft-versus-host disease." (PMID 24852423, 2014). "T-effector and Treg survival and function are both dependent on IL-2, and the balance of the two opposing cell types could be influenced by the relative concentration of IL-2 or by an IL-2 signaling threshold effect that can lead to autoimmunity if disrupted." (PMID 24795433, 2014). "The negative effects of IL-2 on the differentiation of follicular helper T cells (Tfh) and pathogenic Th17 cells, both of which contribute to autoimmunity, is emphasized in the paper as well." (PMID 25322151, 2014). "We also compare the current IL-2-based therapies of animal and human subjects with immune-mediated diseases aimed at boosting the Treg population, which is the most IL-2-dependent cell subset desirable for sufficient control of autoimmunity." (PMID 25322151, 2014). "On the other hand, genome wide association studies (GWAS) have identified a number of potential genes associated with MS including receptors for IL-7 (IL-7RA) and IL-2 (IL-2RA); besides, IL-2 and IL-7 pathways have previously been demonstrated to regulate autoimmunity and EAE in animal models." (PMID 24174969, 2013). "In addition, polymorphisms in IL-2, CD25, or downstream adaptors genes are associated with impaired Treg numbers or function and higher susceptibility to autoimmunity." (PMID 23801992, 2013). "Together, these results support the hypothesis that defects in the IL-2/IL-2R pathway are present in autoimmunity." (PMID 24376757, 2013). "Taken together, Ab/IL-2 immunotherapy may reveal regenerating beta cells otherwise suppressed or killed by autoimmunity." (PMID 24205242, 2013). "Functional data revealed that IL2 variants in NOD mice might affect the interleukin-2 production by antigen-specific T cells and predispose to organ-specific autoimmunity." (PMID 24154763, 2013). "Abrogation of IL-7-dependent signaling results in a SCID phenotype characterized by the lack of T cells and profound immunodeficiency, while abrogation of IL-2-dependent signaling leads to inflammation, multi-organ lymphocyte infiltrates, and autoimmunity in mice and possibly in humans." (PMID 23383227, 2013). "Deficiency for either IL-2 or CD25, which is the specific element of the high affinity IL-2 receptor that also characterizes human aTregs, results in impaired Treg functionality and autoimmunity in mice." (PMID 22479496, 2012). "Consequently, mice deficient for IL-2, CD25, or the IL-2 receptor β subunit, developed uncontrolled lymphoproliferation and lethal autoimmunity." (PMID 22479496, 2012). "In contrast, treatment with anti-IL-2 antibodies inhibited the onset of autoimmunity." (PMID 20856822, 2010).
Autoimmunity (continued). "This could explain the link between inflammation, high IL-2 and IL-17 concentrations, and autoimmunity in our patients." (PMID 21188205, 2010). "IL-2 plays an important role in the development, differentiation and homeostasis of T cells, and IL-2 expression is dysregulated in diseases such as leukaemia, autoimmunity and pathogenesis of viral diseases, including MD." (PMID 20441582, 2010). "Moesin, a member of the FERM (4.1 protein, ezrin, radixin, moesin) domain-containing family of proteins interacting with cytosolic tails of trans-membrane proteins, can activate the IL-2/IL-2R pathway, a system well known to be inefficient in maintaining Treg cells in this model of autoimmunity." (PMID 19379516, 2009). "Ex vivo culture of NK cells with cytokines such as IL-2 and IL-15 is an approach that permits significant expansion of the NK cell subpopulations, which are likely to have potent antitumour, antiviral, or immunomodulatory effects in autoimmunity." (PMID 18053164, 2007). "As such, we have shown that IL-2 stimulated pSTAT5 activity is enhanced in both mouse and human Tregs when treated with NAEi, and that combination therapy with IL-2 and NAEi can reduce disease severity and arrest disease progression in animal models of autoimmunity." (PMID 41169371, 2025). "This escalation will not be performed to find a toxic dose limit since TILs are autologous cells but rather to ensure that the combined treatment (TILs + IL-2 + nivolumab) does not cause severe autoimmunity pathologies, justifying lower doses than those commonly administered." (PMID 39508576, 2024). "Diminished cytokine secretion in exhausted T-cells, may lead to reduced levels of the pro-inflammatory cytokines IL2 and IFNγ, possibly resulting in impaired functioning and activation of autoimmunity by continuous antigen stimulation to the T-cell receptor (TCR)." (PMID 35328504, 2022). "However, high-dose IL-2 administration has been confirmed to enhance immune responses by activating effector T cells against cancer, while low-dose IL-2 was evidenced to mainly stimulate Treg cell survival and expansion and thereby control autoimmunity and inflammation." (PMID 36524114, 2022). "However, recent research has suggested that the modulation of the Foxp3+ regulatory T-cells (Tregs) and the use of cytokine therapy with IL-2 (NCT02772679) may partially prevent ßeta-cell autoimmunity." (PMID 30794611, 2019). "Given the importance of IL-2 in Treg cell stability, immune homeostasis and epigenetic programming, we postulated that Il2ramut/mut mice may develop symptoms consistent with autoimmunity over time." (PMID 30560927, 2018). "Although further data regarding the actual role of IL-2 in EB are needed to explain the discordant results, the increase in IL-2 could represent a further indication of the cytokine imbalance present in EB cases that can lead to autoimmunity and systemic body involvement." (PMID 27669234, 2016). "Therefore, it seems that IL-2 therapy might be an important driver of an imbalance between immune tolerance and destructive autoimmunity depending on its doses." (PMID 25322151, 2014). "The observation of this bimodal response to IL-2, as well as a previous report that Tregs in patients with autoimmunity can display defective IL-2 signaling, led us to hypothesize that a proportion of P3 Tregs may have a defect in signaling in response to IL-2." (PMID 25092890, 2014). "The autoimmunity observed in IL-2/IL-2R KO mice (whether CD25, CD122, or CD132 KO, the different components of the IL-2R) is associated with a profound deficit in Treg numbers and function, suggesting that tTregs generated in the absence of IL-2/IL-2R signaling cannot survive in the periphery." (PMID 23801992, 2013). "Little is known about the way CD25-biased IL-2 agents, like SAR’336, influence the function and nature of Tregs during autoimmunity." (PMID 39704171, 2024).